NR4A2 (nuclear receptor subfamily 4 group A member 2)
Diseases named in the same sentence as NR4A2 in open-access papers (continued):
Sharing a sentence is not in itself a finding about the gene and the disease.
heart failure (6 papers, 2018 to 2026). Inability of the heart to pump blood at an adequate rate to meet tissue metabolic requirements. "It is noteworthy that female mice appeared to be more susceptible to the chronic effects of cardiac NR4A2 as they displayed more severe symptoms of heart failure at 21 days after transgene induction, and died 12.5% faster than male mice." (PMID 35776225, 2022). "NR4A2, on the other hand, has been linked to impaired cardiac function and heart failure." (PMID 39684483, 2024). "Chronic NR4A2 activation leads to activation of cell cycle checkpoints and induction of an apoptotic response resulting in loss of cardiac myocytes, impairment of cardiac function and heart failure." (PMID 35776225, 2022). "The mechanism underlying the role of NR4A2 in apoptosis and autophagy was elucidated, and NR4A2 may be a therapeutic drug target for heart failure." (PMID 29531824, 2018). "In mice, tamoxifen-dependent, cardiomyocyte-restricted overexpression of NR4A2 led to cardiomyocyte hypertrophy, left ventricular dilation, heart failure, and death within 40 days." (PMID 35776225, 2022). "Transcript levels of several established biomarkers, including Spp1, Sfrp1, Sfrp2, Tnc, Vim, Mmp9, and Tnfrsf1a, and several inflammatory markers that are known to be activated in heart failure, such as Cd44, Cd83, Ccl7, Irf7, and Nr4a2, were upregulated in the Myh6-McmTamDspfl/fl cardiomyocytes." (PMID 40608429, 2025). "While the actions of NR4A2 in the heart are unknown, microarray-based studies show its expression is increased with exercise and decreased in models of heart failure." (PMID 36467694, 2022). "Thus, widespread dedifferentiation of myocytes resulting in decreased cardiac bioenergetics and a loss of functional rigor likely contributed to the impairment of systolic function and development of heart failure in Nr4a2-icTg mice." (PMID 35776225, 2022).
liver fibrosis (6 papers, 2015 to 2023). "Indeed, the downregulation of NR4A2 was recently detected in fibrotic liver compared with the normal counterpart and was recently associated with the hepatic stellate cells activation and the liver fibrosis onset." (PMID 28098757, 2017). "Rats overexpressing Nr4a2 treated with dimethylnitrosamine, which induces liver fibrosis, are protected from liver damage." (PMID 31683815, 2019). "Adenovirus-mediated delivery of NR4A2 in rats ameliorated significantly dimethylnitrosamine (DMN) induced liver fibrosis." (PMID 27646469, 2016). "In our study, we raised NR4A2 level through AdNR4A2 treatment in vivo and NR4A2 gene over-expression suppressed liver fibrosis in the end." (PMID 27646469, 2016). "In this study we explored the effect of AdNR4A2, adenovirus carrying NR4A2 gene, on activated HSCs or liver fibrosis and clarified its mechanism." (PMID 27646469, 2016). "To clarify the correlation between NR4A2 and liver fibrosis, we knocked down NR4A2 via three siRNAs and examined the expression of extracellular matrix markers in HSC-T6 cells." (PMID 26713258, 2015). "Taken together these results demonstrate NR4A2 enhancement attenuates liver fibrosis via suppressing the activation of HSCs and NR4A2 may be an ideal target for anti-fibrotic therapy." (PMID 27646469, 2016). "In the present study we explored the role of NR4A2 on liver fibrosis." (PMID 27646469, 2016). "NR4A2 may be a promising therapeutic target for liver fibrosis." (PMID 26713258, 2015). "We also observed that the NR4A2 protein and mRNA level reduced obviously and α-SMA levels elevated significantly when DMN was applied to induce liver fibrosis in rats." (PMID 27646469, 2016). "Our data showed that NR4A2 gene over-expression by adenovirus-mediated significantly suppressed the activated HSCs and attenuated dimethylnitrosamine (DMN) reduced hepatic fibrosis." (PMID 27646469, 2016). "IRF8, NR4A2, IKZF3, and REL may be involved in the transcriptional regulation of NK cells in liver fibrosis." (PMID 35903097, 2022).
Arthritis (5 papers, 2013 to 2022). Inflammation of a joint. "NR4A2 and RelA proteins were overexpressed in inflamed synovium prior to symptoms of arthritis, suggesting that gene expression changes documented in whole paws were largely driven by elevated expression in diseased synovium." (PMID 35529439, 2022). "In conclusion our results provide the first spatiotemporal map of NR4A2 distribution in an animal model of arthritis and validate the hTNF-α model for future testing of synthetic ligands and genetic strategies targeting this transcription factor in vivo." (PMID 35529439, 2022). "Nr4a2 overexpression increased K4IM synoviocyte proliferation, while Nr4a2 knock down decreased proliferation, indicating Nr4a2 as a possible arthritis regulator." (PMID 31683815, 2019). "Nuclear receptor 4A2 (NR4A2) is an orphan nuclear receptor and constitutively active transcription factor expressed at elevated levels in inflamed joint tissues from patients with arthritis." (PMID 25717285, 2015). "In order to further elucidate the molecular mechanisms of NR4A2, we conducted a gene expression screen to identify novel transcriptional targets of NR4A2 that may contribute to arthritis progression." (PMID 25717285, 2015). "Recombinant PRL regulates gene expression pathways that control inflammation, proliferation, and cell survival in synoviocytes, suggesting that NR4A2-induced PRL may elicit similar autocrine responses that may subsequently impact arthritis progression." (PMID 25717285, 2015). "Increasing evidence suggests the role of NR4A2 in inflammatory responses during arthritis and psoriasis, and NR4A2 may also serve as a regulatory element for reducing immune-mediated tissue damage." (PMID 23437182, 2013). "NR4A2 protein was detected in inflamed synovium and cartilage of ankle joints from the TNF-delta-ARE model of chronic inflammation and also in joints from the antigen-induced arthritis model in a pilot study." (PMID 35529439, 2022). "In synoviocytes, recombinant PRL regulates several genes involved in inflammation, proliferation, and cell survival, suggesting that NR4A2 induced PRL may also impact these pathways and contribute to arthritis progression." (PMID 25717285, 2015). "While analyses of human joint tissues and cells have yielded important insight into NR4A2-dependent mechanisms, a comprehensive analysis of receptor mRNA expression levels and protein distribution has not been performed in an animal model of arthritis." (PMID 35529439, 2022). "However, the transcriptional mechanisms of NR4A2 have not been fully elucidated, and this receptor likely regulates several genes that contribute to inflammation and joint degradation in arthritis." (PMID 25717285, 2015).
nasopharyngeal carcinoma (5 papers, 2020 to 2025). A carcinoma arising from the nasopharyngeal epithelium. "LncRNA MSC-AS1 may also worsen the progression of nasopharyngeal carcinoma through upregulation of NR4A2 via sequestration of miR-524-5p." (PMID 40124382, 2025).
prostate carcinoma (5 papers, 2016 to 2025). A carcinoma that arises from epithelial cells of the prostate gland. "For example, the genes TRIB1, NR4A1, and NR4A2 are significantly upregulated in prostate cancer and can serve as biomarkers." (PMID 40167331, 2025). "However, instead of a direct interaction with NFκB as observed in previous studies, we predicted an indirect inhibition of NFκB via NR4A2 as a mechanism in prostate cancer suppression." (PMID 27078000, 2016). "Further expression analysis revealed that a positive expression correlation between NR4A2 (NURR1) and CTNNB1 (β-catenin) was shown in clinical prostate cancer tissues." (PMID 38531859, 2024). "In particular, we predicted the nuclear receptor NR4A2 and the activating transcription factor 3 (ATF3) as novel upstream regulators of NFκB in prostate cancer." (PMID 27078000, 2016). "Notable genes in the predicted pathway included ATF3, JUNB, KLF6, NR4A2, ZFP36, DUSP5 and NEDD9, as well as STAT3 and IRF1 as novel upstream regulators, and SELE, CXCL1 and CXCL2 as novel downstream targets of NFκB in prostate cancer." (PMID 27078000, 2016).
Autoimmunity (4 papers, 2020 to 2022). The occurrence of an immune reaction against the organism's own cells or tissues. "NR4A2 controls IL‐21 secretion by Th cells in a model of organ‐specific autoimmunity." (PMID 36069030, 2022). "However this is in slight contradiction with the fact that autoimmunity and reduced lifespan was observed in Nr4a1/Nr4a3 but not in Nr4a2/Nr4a3 double deficient mice." (PMID 33597928, 2020). "Next, we then assessed if these cells were sufficient to generate autoimmunity where disease onset is blocked by a lack of NR4A2 in T cells." (PMID 36069030, 2022). "Molecules that specifically inhibit Nr4a1 and Nr4a2, but not Nr4a3, are also candidates for tumor Treg-specific inhibitors, as Foxp3CreNr4a-DcKO mice do not develop autoimmunity but the mice do develop augmented antitumor immunity." (PMID 35514961, 2022).
Dystonia (4 papers, 2022 to 2025). An abnormally increased muscular tone that causes fixed abnormal postures. "Furthermore, we identified a novel, likely pathogenic missense variant in NR4A2, a gene recently associated with levodopa‐responsive dystonia and developmental delay." (PMID 40533913, 2025). "Screening our data for proposed dystonia candidate genes identified presumably pathogenic variants in CHD6, KCNN2, KLC1, NR4A2, and ZMYND11, but not in others, for example, ATP5F1B, ACBD6, CIZ1, SHQ1, and SPTBN1." (PMID 40533913, 2025). "Notably, our data support a role of pathogenic variants in CHD6, KLC1, NR4A2, and ZMYND11 in dystonia even without neurodevelopmental features, while the relevance of identified VUS in several candidate genes remains unclear." (PMID 40533913, 2025).
myocardial infarction (4 papers, 2018 to 2025). Gross necrosis of the myocardium, as a result of interruption of the blood supply to the area, as in coronary thrombosis. "More recently, NR4A2 has been proposed to protect cardiomyocytes from myocardial infarction injury by promoting autophagy." (PMID 31188636, 2019).
ovarian carcinoma (4 papers, 2008 to 2024). A malignant neoplasm originating from the surface ovarian epithelium. "While VEGF and VEGFR play an essential role in ovarian cancer progression, recent studies have shown that promoters of angiogenesis such as angiopoietins, apelin receptors, and its ligand apelin, NR4A2, also play an equally important role." (PMID 35052372, 2021).
pancreatic cancer (4 papers, 2020 to 2025). "The close 4-chlorophenyl analog 3f selectively activated NR4A2 (Nurr1) in pancreatic cancer cells and had only marginal effects on NR4A1 and NR4A3 activity." (PMID 35582221, 2020). "Interestingly NR4A2 also regulates autophagy and DIM12 decreases ATG7 and ATG12 gene expression in pancreatic cancer cell and tumors, whereas celastrol induced NR4A1-dependent autophagy, demonstrating opposing effects of NR4A1 and NR4A2 ligands which may also be cell context dependent." (PMID 38116863, 2024).
adenoma (3 papers, 2013 to 2024). A neoplasm arising from the epithelium. "Nr4a2 has been reported to upregulate aldosterone synthase expression in NCI-H295R cells and proposed to have clinical importance, since its expression levels are upregulated in aldosterone-producing adenomas and correlate with aldosterone synthase expression levels." (PMID 38573585, 2024).
Dyskinesia (3 papers, 2014 to 2023). A movement disorder which consists of effects including diminished voluntary movements and the presence of involuntary movements. "Notably, recent evidence indicates that viral vector-induced overexpression of Nr4a2 in striatal neurons increases dyskinesia in a rat model of PD." (PMID 25254549, 2014).
head and neck cancer (3 papers, 2019 to 2023). A primary or metastatic malignant neoplasm affecting the head and neck. "Relatively frequent mutations were also detected in several other IntOgen-defined cancer drivers such as MGA, PABPC3, NR4A2, NCOR1 and MACF1; of these PABPC3, NR4A2, NCOR1 and MACF1 are detected as mutational cancer drivers in head and neck cancer in IntOgen." (PMID 31427592, 2019).
osteoarthritis (3 papers, 2015 to 2022). A noninflammatory degenerative joint disease occurring chiefly in older persons, characterized by degeneration of the articular cartilage, hypertrophy of bone at the margins and changes in the synovial membrane. "NR4A2 is also highly expressed in inflamed synovial tissues from individuals with RA and psoriatic arthritis as well as in cartilage from individuals with osteoarthritis (OA)." (PMID 35529439, 2022). "Further, if the existence of cluster O3 is due to the osteoarthritis, specific markers NR4A1 and NR4A2, would have important roles in osteoarthritis pathogenesis." (PMID 34428745, 2021). "While previous studies have reported NR4A1 and NR4A2 to be regulators of inflammatory responses in chondrocytes, no study has proposed the relationship between osteoarthritis and NR4A1 produced by osteoblasts." (PMID 34428745, 2021).
osteosarcoma (3 papers, 2020 to 2024). A usually aggressive malignant bone-forming mesenchymal neoplasm, predominantly affecting adolescents and young adults. "In “Myeloid”, differentially expressed NRs such as NR4A2, NR4A1, NR3C1, RXRA, NR1D2, PPARD, and RARA were identified among metastasis, primary, and recurrent osteosarcoma tissues." (PMID 35965537, 2022). "Based on our analysis, we found that several NRs including NR4A2, NR4A1, NR3C1, NR2F6, and NR2F2 were differentially expressed in osteoblastic cells among metastasis, primary, and recurrent osteosarcomas." (PMID 35965537, 2022). "Furthermore, several NRs such as NR4A2, NR4A1, and NR3C1 have been found to be differentially expressed in most types of DEGs among metastasis, primary, and recurrent osteosarcomas." (PMID 35965537, 2022). "Furthermore, several NRs such as NR4A2, NR4A1, and NR3C1 have been found to be differentially expressed in most types of DEGs among metastasis, primary, and recurrent osteosarcoma." (PMID 35965537, 2022). "Up to date, the role of NR4A2 has not been studied in osteosarcoma." (PMID 35965537, 2022).
Sepsis (3 papers, 2015 to 2025). Sepsis is defined as life-threatening organ dysfunction caused by a dysregulated host response to infection. "Among these upregulated genes, prior research demonstrated that Nr4a2 has been linked to M2 polarization and protection in sepsis models, while Ccl17 and Csf1 are implicated in the recruitment of Th2 cells." (PMID 41026710, 2025). "Altered expression of NR4A2 and -3 has been shown to guide macrophage polarization with adoptive transfer experiments revealing that NR4A2 confers increased survival in endotoxin (LPS) induced sepsis." (PMID 26131976, 2015). "PDPNA binds NR4A1, NR4A2, and NR4A3 but inhibits sepsis only through NR4A1." (PMID 38540704, 2024).
Ataxia (2 papers, 2025). Ataxia refers to impaired coordination of voluntary muscle movement. "One variant each was identified in the genes CHD6 (p.Glu2697Thrfs*29 in a patient with adolescence‐onset generalized dystonia with myoclonus and ataxia), KLC1 (c.*1+1G>A in a patient with adult‐onset cervical dystonia), and NR4A2 (p.Gln273Arg in a patient with adult‐onset cervical dystonia)." (PMID 40533913, 2025).
autism spectrum disorder (2 papers, 2021 to 2025). A spectrum of developmental disorders that includes autism, and Asperger syndrome. "The current report provides additional evidence regarding the role of the NR4A2 gene in autism spectrum disorder (ASD) among children in Saudi Arabia." (PMID 40564942, 2025).
cardiac hypertrophy (2 papers, 2019). "Interestingly, NR4A2 overexpression also potently inhibited expression of the cardiac hypertrophy marker B-type natriuretic peptide (BNP) in both vehicle- and isoproterenol-treated ARVMs." (PMID 31188636, 2019).
cocaine addiction (2 papers, 2017 to 2021). "Our results further demonstrated that Nr4a1 persistently increased while Nr4a2 and Nr4a3 showed transient changes after cocaine withdrawal, indicating their different roles in different stages of cocaine addiction." (PMID 28386228, 2017).
dependence (2 papers, 2019 to 2022). "Combined with previous studies, we speculated that the Nr4a2 was a potential target gene for substance dependence." (PMID 35432486, 2022).
developmental delay (2 papers, 2025). "In the present study, exome sequencing and genome-wide copy number variation analysis were employed to identify a missense variant and a microdeletion involving the NR4A2 gene in two patients who exhibited global developmental delay and speech deficits." (PMID 41019763, 2025).
endothelial dysfunction (2 papers, 2021 to 2023). In vascular diseases, endothelial dysfunction is a systemic pathological state of the endothelium (the inner lining of blood vessels) and can be broadly defined as an imbalance between vasodilating and vasoconstricting substances produced by (or acting on) the endothelium. "Our model of endothelial dysfunction revealed that TNF-α-induced endothelial dysfunction did not alter NR4A2 expression." (PMID 34667209, 2021). "NR4A2 expression was also not altered in a model of tumour necrosis factor-α-induced endothelial dysfunction, or with pravastatin treatment." (PMID 34667209, 2021). "This suggests that the endothelium is also unlikely to be the origin of the increased circulating NR4A2 transcripts—but additional studies using additional endothelial cell types beyond HUVECs, and different inducers of endothelial dysfunction are required before this can be confirmed." (PMID 34667209, 2021).